SCPEP1 (serine carboxypeptidase 1)
Description:
May be involved in vascular wall and kidney homeostasis.
Synonyms: RISC; HSCP1
Tractability: Antibody: UniProt places it where antibodies can reach, with high confidence; UniProt predicts a signal peptide or a membrane-spanning region; its Gene Ontology location is reachable by antibodies, with medium confidence. PROTAC: ubiquitination databases record sites on it; its protein half-life has been measured.
Target class: Enzyme; Serine protease; Serine protease SC clan; Protease; Serine protease S10 family
Gene: Protein-coding gene on chromosome 17 (56,978,111 to 57,006,768, forward strand). Ensembl gene ENSG00000121064.
Subcellular location: Secreted
Subcellular location (Human Protein Atlas): Golgi apparatus; Predicted to be secreted
Gene Ontology:
Molecular function: serine-type carboxypeptidase activity
Biological process: blood vessel diameter maintenance; negative regulation of blood pressure; retinoic acid metabolic process; proteolysis
Cellular component: extracellular exosome; extracellular region
Genetic constraint (gnomAD): Loss-of-function variants: 39 observed, 47.43 expected, observed/expected ratio (o/e) 0.82, 90% interval 0.64 to 1.07. The upper end of that interval is the gene's LOEUF score, 1.07, which puts it in group 4 of 6, group 1 being the genes least tolerant of losing a copy. Missense variants: 404 observed, 464.35 expected, observed/expected ratio (o/e) 0.87, 90% interval 0.8 to 0.94. Synonymous variants: 160 observed, 169.91 expected, observed/expected ratio (o/e) 0.94, 90% interval 0.83 to 1.07.
Homologues: Orthologues: chimpanzee SCPEP1 (99% identical), macaque SCPEP1 (96% identical), dog SCPEP1 (89% identical), rabbit SCPEP1 (88% identical), mouse Scpep1 (82% identical), guinea pig SCPEP1 (81% identical), rat Scpep1 (81% identical), pig SCPEP1 (78% identical), zebrafish scpep1 (62% identical), tropical clawed frog scpep1 (56% identical), Caenorhabditis elegans Y32F6A.5 (42% identical), Drosophila melanogaster CG32483 (37% identical), and 4 more. Paralogues in human: CPVL (25% identical), CTSA (24% identical).
Diseases named in the same sentence as SCPEP1 in open-access papers:
SCPEP1 is named in the same sentence as 16 diseases in open-access papers, as found by Europe PMC text mining. Sharing a sentence is not in itself a finding about the gene and the disease. The quoted sentences say what the papers report.
Hypertension (2 papers, 2014 to 2017). The presence of chronic increased pressure in the systemic arterial system. "In particular, we showed that mice with double deficiency of CathA and Scpep1 developed a persisted hypertension and demonstrated a prolonged half-life of circulating ET-1 as well as a more pronounced vasoconstriction in response to low pharmacological doses of this peptide." (PMID 28234994, 2017). "The expression of Scpep1 in cardiovascular tissues can be effectively induced by retinoic acid, potentially providing a metabolic bypath to correct arterial hypertension attributed to a deficiency in ET-1 degradation in galactosialidosis patients with mutations in the CATHA gene." (PMID 24586188, 2014).
Stroke (2 papers, 2012 to 2014). Sudden impairment of blood flow to a part of the brain due to occlusion or rupture of an artery to the brain. "Our studies also suggest that the new “stroke genes” Fnbl5, Fndc1, Pcolce, Scpep1, and Igfbp7 induce EC-lumen formation by increasing the stiffness of the ECM and increasing BV elasticity." (PMID 24672479, 2014).
Blindness (1 paper, 2017). Blindness is the condition of lacking visual perception defined as a profound reduction in visual perception. "We have discovered that about 30% of senescent (6 months and older) CathA/Scpep1-deficient mice exhibited corneal cloudiness that finally led to their blindness." (PMID 28234994, 2017).
diabetes (1 paper, 2023). "Lower expression in patients with diabetes was evident for SCPEP1, S100A11, LEP, PEBP1, SHGB, and APOF." (PMID 37792298, 2023).
Fibroadenoma (1 paper, 2020). A benign tumor of the breast characterized by the presence of stromal and epithelial elements. "We detected an increase in the expression of six proteins (NUDT19, FBN1, NONO, FLNA, SCPEP1, and galactosidase alpha) in fibroadenoma." (PMID 33194682, 2020).
idiopathic pulmonary fibrosis (1 paper, 2025). Idiopathic pulmonary fibrosis (IPF) is a nonneoplastic pulmonary disease that is characterized by the formation of scar tissue within the lungs in the absence of any known cause. "To further validate the expression of Scpep1 at both the protein and transcriptional levels, we performed and Western blotting (WB) quantitative real-time PCR (qPCR) using lung tissues from the bleomycin-induced pulmonary fibrosis model." (PMID 41438766, 2025). "In this study, we integrated multi-omics datasets—including single-cell RNA sequencing, spatial transcriptomics, and bulk RNA-seq to comprehensively profile oxidative stress (OS) activity in idiopathic pulmonary fibrosis (IPF) and identify SCPEP1 as a robust OS-related biomarker." (PMID 41438766, 2025).
tumor (4 papers, 2023 to 2025). "The results showed that the SCPEP1 gene was highly expressed in BRCA, KIRC and THCA tumour types, and the DUSP2 gene was more expressed in KICH, LIHC and BRCA." (PMID 37091857, 2023).
cancer (2 papers, 2020 to 2025). A tumor composed of atypical neoplastic, often pleomorphic cells that invade other tissues. "SCPEP1 is associated with cancer development, growth, and metastasis." (PMID 39723668, 2025). "For DCIS tissues, compared with both DCIS cancer-adjacent and normal tissues, we detected four up-regulated (GAPDH, HSPA9, CCT4, and SCPEP1) and 48 down-regulated proteins (including KRT10, APOA1, ALDH1A1, and others) in DCIS tissues." (PMID 33194682, 2020).
renal disease- (1 paper, 2021). "Seven of those renal disease-related proteins had higher weighted scores (> 0.60), including Ggt1 (0.941), Camp (0.906), Cdh1 (0.835), Lpo (0.833), Scpep1 (0.803), Anpep (0.644), and Ptgds (0.603)." (PMID 33981220, 2021).
SCPEP1 also shares sentences with these, for which no sentence is quoted: atypical hemolytic-uremic syndrome (1 paper); galactosialidosis (1); microangiopathic hemolytic anemia (1); neuroblastoma (1); neurological disorders (1); renal failure (1); Thrombocytopenia (1).